INS (insulin)
Diseases named in the same sentence as INS in open-access papers (continued):
Sharing a sentence is not in itself a finding about the gene and the disease.
infection (continued). "Most cases attributed the development of EuDKA to one or more precipitating factors, of which the most frequently identified were surgical stress (n = 15), reduced caloric intake (n = 10), infection (n = 6) and inadequate intraoperative insulin (n = 3)." (PMID 40887509, 2025). "Previous studies have shown that the insulin signaling pathway is crucial for the development of iL3 in S. stercoralis during infection." (PMID 41406115, 2025). "Treatment with nebulized amphotericin B combined with intensive insulin therapy successfully controlled the infection and stabilized blood glucose levels." (PMID 41585813, 2025). "Early recognition and prompt management with fluid resuscitation, insulin therapy, and infection control are critical to preventing life-threatening acidosis." (PMID 41556033, 2025). "After discharge, glucose levels stabilized at 6–7 mmol/L through intensive insulin therapy, with concurrent improvement in infection markers." (PMID 41585813, 2025). "The increased expression of ImpL2 RA and ImpL2 RB upon infection in muscles of control animals is further evidence of the antagonistic role of ImpL2 in insulin signaling." (PMID 38566182, 2024). "In case of infection, the release of inflammatory mediators and cytokines leads to a higher hepatic gluconeogenesis and insulin resistance." (PMID 39768755, 2024). "Here, we demonstrate that D. melanogaster with a mutation in the insulin suppression gene Lst is hyperinsulinemic and shows upregulated expression of genes within the antiviral JAK/STAT pathway during infection." (PMID 38921161, 2024). "To show the importance of insulin signaling during WNV-NY99 infection in insect cells, we treated multiple mosquito cell lines and D. melanogaster S2 cells with 1.7 μM bovine insulin prior to WNV infection." (PMID 39664493, 2024). "Accordingly, we sought to examine host responses to infection under insulin selection in Cx. quinquefasciatus, the primary vector of WNV in North America." (PMID 39664493, 2024). "Other persistent epithelial defect (PED) etiologies that have been treated with topical insulin are infection, immune-mediated, mechanical and chemical trauma, and chronic ocular surface alterations." (PMID 38989397, 2024). "We showed that expression of Thor is increased upon infection, which indicates a link to insulin signaling." (PMID 38566182, 2024). "This is associated with a reduction in the host innate immune response, demonstrated by the decreased transcription of antimicrobial peptides as well as a significant reduction in the ability of the infection to disrupt systemic insulin signaling." (PMID 39514319, 2024). "Insulin was also reduced in pancreas by the infection of H. pylori, and only a redistribution was detected by the treatment with ethanol." (PMID 39030443, 2024). "Beta cell stress has been proposed as a mechanism connecting environmental perturbations such as infection, inflammation, diet, and increased insulin secretion to disease progression." (PMID 38915393, 2024). "This GO category is highly enriched in insulin-fed mosquitoes during WNV-Kun infection as well as a similar GO category, response to oxidative stress, in D. melanogaster S2 cells treated with insulin during WNV-Kun infection." (PMID 39664493, 2024). "In the wild type situation levels of both ImpL2 RA and ImpL2 RB increase upon infection as more ImpL2 is produced in order to reduce insulin signaling and therefore free up metabolites that can be directed towards the immune system." (PMID 38566182, 2024). "Our study demonstrated that pre-treatment of THA and TUN prior to infection resulted in an enhanced insulin-stimulated glucose uptake, most likely through induction of GLUT translocation." (PMID 38727305, 2024). "Together, these results suggest suppression of insulin signaling in peripheral tissues, such as muscles, is necessary to facilitate metabolic reprograming during infection." (PMID 38566182, 2024).
infection (continued). "Here we show that the initiation of JAK/STAT signaling, by upd, in muscles leads to the suppression of insulin signaling during infection, which is essential for survival." (PMID 38566182, 2024). "We observed that using an MOI of 5, ~40% of islets were infected after 24 h of infection, and ~80% of sc-islets, including insulin-positive cells, were infected after 48 h of infection." (PMID 39682726, 2024). "Similar to previous findings using WNV-Kun, we found that insulin treatment reduced WNV-NY99 viral load throughout infection." (PMID 39664493, 2024). "Infection status would substantially alter the norm of blood glucose dynamics despite injecting insulin and reducing carbohydrate consumption." (PMID 38570745, 2024). "Here we demonstrate the importance of host mediated insulin resistance as an adaptive mechanism, crucial for survival during infection." (PMID 38566182, 2024). "Consistent with our clinical data, the results showed that infection was more severe in Huh7 cells at high glucose levels, while insulin levels had a minimal impact on SARS-CoV-2 infection." (PMID 39150053, 2024). "The interplay between immune response and insulin signaling has evolved as a means of the energy distribution during infection." (PMID 38958928, 2024). "Ceftriaxone, a sensitive antibiotic, was administered for infection control, along with intravenous fluids and blood transfusions to correct the shock state, and insulin was given to stabilize blood glucose levels." (PMID 39839632, 2024). "In this case, systemic reduction in insulin signaling should render flies equally sensitive to infection with either strain." (PMID 39514319, 2024). "Cells were primed with media containing 1.7 μM bovine insulin or vehicle control 24 hours prior to infection with virus." (PMID 39664493, 2024). "The glucagon pathway operates downstream of the insulin signaling pathway, which plays a central role in metabolic regulation during infection and inflammation." (PMID 39769543, 2024). "We used a Gal80[ts] system to induce apoptosis of insulin-producing cells (IPCs) in adult flies prior to infection." (PMID 39514319, 2024). "This is likely due to suppression of insulin signaling in muscles, as a means to divert metabolites away from muscles in favor of the immune system as metabolic demand increases during infection." (PMID 38566182, 2024). "As was observed in upd null mutants, muscle specific expression of InRDN leads to a rescue in both lamellocyte number and survival rate, once again demonstrating the role of ImpL2 in insulin resistance during infection." (PMID 38566182, 2024). "We propose that upd/JAK/STAT signaling regulates insulin signaling in muscles during infection, which in turn is vital for effective immune response." (PMID 38566182, 2024). "The most common are infection, the discontinuation of or inadequate insulin therapy, pancreatitis, myocardial infarction and cerebrovascular accidents." (PMID 38786741, 2024). "Here, we give further insights into the metabolic reprogramming that occurs during infection, namely the suppression of insulin signaling and redirection of energy stores away from muscles." (PMID 38566182, 2024). "Hyperinsulinemic-euglycemic clamp assays confirmed the significant increase in insulin sensitivity after Ad-RIMKLA infection." (PMID 39117631, 2024). "Elettra Barberis and her colleagues utilized metabolomic approaches to identify lipid biomarkers in COVID-19 patients, providing evidence of insulin resistance development post-infection." (PMID 38287388, 2024). "Even though it's not mandatory, skin cleaning is usually recommended before an insulin injection to prevent infection of the injection site." (PMID 37143082, 2023). "Glucose tolerance tests (GTT) and insulin tolerance tests (ITT) were performed in all the groups two weeks before harvest (6 weeks post infection [p.i.]) and in uninfected mice." (PMID 37730757, 2023).
infection (continued). "After 48h of infection, cells were treated with either glucagon, Forskolin, insulin, or metformin and were subjected to glucose output assay." (PMID 36866247, 2023). "At 3 days post infection, liver insulin sensitivity was impaired and a tendency towards glucose intolerance was observed, particularly reflected in reduced glucose uptake." (PMID 36768699, 2023). "Oral infection with Vibrio cholerae induces intestinal acetate depletion in D. melanogaster, systemically inhibits the insulin pathway, promotes fat accumulation in intestinal ECs cells, and accelerates infection-induced host death." (PMID 37818375, 2023). "Infection with SARS-CoV-2 resulted in impaired insulin/insulin growth factor signaling pathway genes, including IRS, PI3K, AKT, mTOR, and MAPK in several key tissues, such as lung, liver, adipose tissue, and pancreas." (PMID 36768699, 2023). "Insulin discontinuation and infection remain the two most common triggers for diabetic ketoacidosis." (PMID 37510185, 2023). "Management included insulin infusion, cautious fluid replacement therapy, electrolyte monitoring, and identifying precipitating factors, such as an infection." (PMID 37654917, 2023). "We performed a cohort study using the Korean health insurance data to investigate infection risks with each drug class relative to metformin in insulin-treated T2DM patients." (PMID 37891260, 2023). "The patient was treated with fluid resuscitation, insulin, anti-infection treatments, somatostatin, omeprazole, low-molecular-weight heparin, and nutritional support." (PMID 37286981, 2023). "Regarding the role of insulin and metformin in the defense against infections, a murine pre-diabetic model revealed that urinary tract infections are more frequent when the insulin receptor is deleted." (PMID 36982317, 2023). "A rescue experiment revealed that insulin secretion was reduced upon replenishing Rab26 by infection of Ad-Rab26 in Rab26-KO INS-1 cells." (PMID 37289842, 2023). "The study also documented insulin resistance in lung tissues, which can affect immunity, leading to repeated infection." (PMID 37362491, 2023). "Our findings begin to identify additional roles for the regulation of intermediary metabolism, in addition to its critical role in the regulation of insulin secretion, in the protection of β-cells from damage and infection." (PMID 36773802, 2023). "Strikingly, infection of preadipocytes impaired their differentiation towards fully mature and insulin-sensitive adipocytes through a TNFα-mediated inflammatory mechanism." (PMID 36936928, 2023). "Serial glucose tolerance tests, and insulin and pyruvate challenge tests were performed 1 week before infection and at 2 and 6 weeks after infection." (PMID 37556193, 2023). "Activation of Toll in the D. melanogaster fat body either through genetic manipulation or infection suppresses insulin signaling as measured by reduced phosphorylation of Akt." (PMID 37915572, 2023). "There was a significant reduction in serum insulin concentration in Tz mono-infected (P < 0.05) and co-infected (P < 0.05) experimental groups at day 0 post Pb infection in comparison to both the control and Pb infected groups." (PMID 35923890, 2022). "Hosts infected with Plasmodium demonstrate increased blood insulin concentrations, which trigger the insulin/IGF-1 signaling pathway in Anopheles mosquitos, hereby increasing mosquito susceptibility to infection, lifespan and transmission." (PMID 35385472, 2022). "We noticed that except for the pro-inflammatory pathway, infection factors and lysosome, insulin signalling was significantly activated in C2." (PMID 36474294, 2022). "The patient was treated with fluid therapy, ketosis correction, insulin, and anti-infection treatment." (PMID 36595822, 2022). "After fluid therapy, ketosis correction, insulin, and anti-infection treatment, the patient gradually recovered." (PMID 36595822, 2022).
infection (continued). "Another gene-of-interest is insulin, which was up-regulated at intermediate infection in spleen with extremely high fold change of ~560." (PMID 36296170, 2022). "While the significant detrimental effects of schistosome infections on host tissue are unarguable, there is evidence of sustained metabolic alterations post-infection, notably, increased glucose metabolism and insulin sensitivity." (PMID 35167594, 2022). "Other less common precipitants include trauma, exposure to cold, infection, menstruation, and the use of drugs such as diuretics, insulin, or corticosteroids." (PMID 35702451, 2022). "Multiple daily subcutaneous insulin injections, empirical anti-infection and immunosuppression treatment with corticosteroids were performed." (PMID 36482651, 2022). "We found that ubiquitous overexpression of ImpL2 was sufficient to block insulin signalling (as measured by Akt phosphorylation) and to prevent that infection-mediated increase in TOR signalling, as measured by S6K phosphorylation." (PMID 35363274, 2022). "Second, there are other bacteria present in the microflora that, by their synergistic action, can also change insulin secretion, while in cell culture is present only one type of infection." (PMID 36397429, 2022). "At intermediate infection, insulin secretion was activated in the HK and spleen and in the latter, additional insulin-related processes such as insulin signaling pathway and insulin resistance were up-regulated." (PMID 36296170, 2022). "The reduced metabolite levels can be also attributed to insulin signaling, which regulates both carbohydrate and lipid metabolism to maintain nutritional homeostasis and energy reserves during infection." (PMID 35844546, 2022). "Insulin omission was the most frequent cause of DKA (39 [30.2%]), followed by infection (30 [23.3%])." (PMID 36066894, 2022). "The co-infected group serum insulin concentration was significantly reduced (P < 0.05) at day 14 Pb infection in comparison to the control group." (PMID 35923890, 2022). "To investigate the impact of CVB3/28 infection on endocrine pancreases, we performed confocal analyses allowing us to explore beta cells’ insulin expression." (PMID 36560784, 2022). "We recently demonstrated that insulin downregulates the infection of UPEC in bladder cells in a high-glucose environment via the Janus kinase (JAK)/signal transducer and activator of transcription (STAT) signaling pathway." (PMID 36555403, 2022). "The infection with SARS-CoV-2 impairs the glucose–insulin axis and this contributes to oxidative (OS) and nitrosative (NSS) stress." (PMID 35326383, 2022). "Infection with M. luteus inhibits insulin signalling, as evidenced through a reduction in phosphorylated AKT, and this metabolic shift is concomitant to a reduction in triglyceride levels." (PMID 36129961, 2022). "In comparison to control group, reduction in serum insulin concentration in Pb mono-infected group persisted at day 7 post Pb infection in comparison control group." (PMID 35923890, 2022). "The pathway of insulin secretion was up-regulated in both hematopoietic organs at intermediate infection and insulin gene was significantly up-regulated in the spleen with an extremely high fold change of ~560." (PMID 36296170, 2022). "Using an immunocompetent mouse model of systemic CVB3/28 infection, we recently showed that a persistent pancreatic infection by these CVB-TD RNA forms was associated with an insulin content decrease." (PMID 36560784, 2022). "Another randomized controlled trial performed in 78 SAH patients after surgical clipping found that intensive insulin therapy (4.4–6.7 mmol/L; 80–120 mg/dl) significantly reduced infection rates as compared with maintaining BG <11.1 mmol/L (200 mg/dl)." (PMID 34675863, 2021). "In Japan, skin disinfection is typically considered necessary before an insulin injection to prevent infection at the injection site." (PMID 33916158, 2021).
infection (continued). "Patients who received corticosteroids had longer LOS in the ICU, had more infections, and had more insulin use." (PMID 34631828, 2021). "Upon infection, insulin transcript levels were reduced with a concomitant increase in alpha cell markers such as GCG, SMARCA1, RGS4, KLHL41, RFX6, TM4S4 and acinar cell markers such as PRSS1, PRSS2, SPINK1, CPB1, CPA1, CPA2, OLFM4." (PMID 34561952, 2021). "Our prior studies also showed that infection causes fmo-2/FMO5 induction independently of previously identified host defense pathways, including p38 MAPK, TGF-β, ERK, insulin, Wnt, and HIF-1 pathways." (PMID 33978570, 2021). "The INS peptide was able to stimulate the integration of the viral DNA by targeted lentiviral particles approximately threefold, 72 h post-infection." (PMID 33958722, 2021). "The DMGs were enriched for GO terms related to calcium-mediated signaling, chromosomal rearrangement, infection and inflammation pathways, phosphoprotein, carbohydrate-insulin pathways, lipid metabolism pathways and amino acid metabolism pathways." (PMID 33435586, 2021). "The high incidence of insulin usage suggests advanced diabetes disease and more correlated problems such as higher infection rates, but it was also responsible for the good control of patients' blood glucose." (PMID 33656831, 2021). "It should be noted that medications like glucocorticoids, severe illness, and infection often necessitate timely and reasonable adjustment of hypoglycemic drugs and/or insulin dosage based on their impairment of insulin sensitivity." (PMID 34373739, 2021). "Redundancy of ImpL2 and Upd3 effects suggests that it is adaptive to inhibit insulin signaling in adipose tissue by multiple SIFs to secure mobilization of sources upon infection." (PMID 33659253, 2021). "CM mainly affected infection and immunity-related pathways, as well as insulin resistance and cholesterol metabolism." (PMID 34222250, 2021). "It is well documented that insulin and insulin signaling can influence immunity and infection in different arthropods including Anopheles mosquitoes." (PMID 34473801, 2021). "Additional inhibited processes included insulin-related pathways and the acute phase response (inflammatory/infection) signaling." (PMID 34209203, 2021). "In turn, if the prescription was a direct treatment for a specified condition e.g. an infection, or essential to prevent a medical emergency e.g. insulin for a type 1 diabetic, it is likely that subsequent ED visits would be averted in a short time period." (PMID 33413396, 2021). "Our study demonstrated that insulin not only reduced UPEC infection in bladder epithelial cells but also decreased the JAK/STAT transduction pathway during infection in a high-glucose environment." (PMID 34946023, 2021). "In the present study, we report the persistent infection with CV-B4 of insulin-secreting β cells (INS-1 cell line)." (PMID 34067388, 2021). "Recently, it was shown that insulin mRNA expression and C-peptide levels were inhibited by persistent CV-B4 E2 infection in human primary pancreatic ductal cells differentiated into ICA in vitro." (PMID 34067388, 2021). "Future studies focusing on the environment, in which patients administer insulin injections, to assess its influence on symptoms of injection site infections are warranted." (PMID 33916158, 2021). "The repeated use of insulin needles can lead to distortion, bending, breakage, and complications, including pain, bruising, bleeding, infection, and lipohypertrophy." (PMID 34497858, 2021). "In the chronic stages of infection, Mtb infected metformin-treated animals had restored systemic insulin sensitivity but remained glucose intolerant as determined by oral glucose tolerance testing." (PMID 33004826, 2020). "The frequency of DKA recurrence was found to be only one episode per year and precipitated commonly by poor insulin therapy and infections." (PMID 32999787, 2020).